PDE10A (phosphodiesterase 10A)
Diseases named in the same sentence as PDE10A in open-access papers (continued):
Sharing a sentence is not in itself a finding about the gene and the disease.
psychiatric disorder (7 papers, 2011 to 2025). A disorder characterized by behavioral and/or psychological abnormalities, often accompanied by physical symptoms. "For instance, in the brain, PDE10A has been reported to be involved in the regulation of cAMP and cGMP synthesis and is commonly used as a therapeutic inhibitor for psychiatric disorder treatment." (PMID 37601105, 2023). "Recent studies demonstrated a putative role for PDE10A in the treatment of neurological and psychiatric disorders." (PMID 28439226, 2017). "PDE10A may be involved in other neurological and psychiatric disorders, including Huntington’s disease, Parkinson’s disease, addiction, and Lesch–Nyhan disease." (PMID 28439226, 2017). "The unique distribution of PDE10A in the brain and its enrichment in the striatum indicate that PDE10A inhibitors are potential therapeutic agents for the treatment of neurological and psychiatric disorders." (PMID 21494592, 2011). "In addition, PDE10A abnormal expression in neurological and psychiatric disorders." (PMID 35463083, 2022). "A phosphodiesterase 10A (PDE10A) inhibitor PF-2545920 has recently attracted attention as a potential therapy for neurological and psychiatric disorders." (PMID 28439226, 2017).
neurological diseases (4 papers, 2013 to 2026). "Interestingly, PDEs, including PDE10A, have previously been shown to be highly expressed in the brain, and are implicated in other neurological diseases." (PMID 23691025, 2013). "PheWAS results showed that FAM227B is significantly associated with cardiovascular phenotypes, that PDE8B is enriched in endocrine/metabolic pathways, and that PDE10A has strong genetic links to neurological diseases." (PMID 41570039, 2026). "This minimal expression of PDE10A in the hippocampus could, however, counteract its potential benefits in other neurological disorders that should be considered." (PMID 41179677, 2025).
cardiovascular diseases (2 papers, 2022 to 2026). "PheWAS linked FAM227B to cardiovascular diseases and PDE10A to neurological pathways." (PMID 41570039, 2026).
genetic disorders (2 papers, 2022). "We collected and reviewed 74 articles (17 for GNB1, 46 for GNAO1, 6 for PDE10A, 2 for PDE2A, and 3 for HCPCA) describing motor, epileptic, and developmental phenotype of patients with genetic disorders of GPCRs–cAMP signaling pathway." (PMID 36003298, 2022).
PDE10A also shares sentences with these, for which no sentence is quoted: colon carcinoma (4 papers); osteosarcoma (4); hypothyroidism (3); non-small cell lung carcinoma (3); Parkinson's (3); pulmonary hypertension (3); adenoma (2); Alzheimer disease (2); brain disorder (2); esophageal squamous cell carcinoma (2); osteonecrosis (2); prostate carcinoma (2); adenocarcinoma (1); amyotrophic lateral sclerosis (1); Ataxia (1); autism (1); autism spectrum disorder (1); autosomal dominant striatal degeneration-2 (1); basal cell carcinoma (1); central nervous system disorder (1); cervical cancer (1); cholangiocarcinoma (1); cocaine use disorder (1); colorectal polyps (1); colorectal tumors (1); COVID-19 (1); Delusion (1); encephalitis (1); Encephalopathy (1); femoral neck fracture (1).
A further 29 diseases each share a sentence with PDE10A in 1 paper.